RETN (resistin)
Diseases named in the same sentence as RETN in open-access papers (continued):
Sharing a sentence is not in itself a finding about the gene and the disease.
Obesity (continued). "Since its discovery, resistin has been related to obesity and IR in many animal experiments, but the application of these findings to human studies has been difficult to determine." (PMID 28587203, 2017). "Some evidence suggests that resistin modulates glucose tolerance and insulin action, thereby playing a role in the pathogenesis of obesity and insulin resistance in humans." (PMID 29386698, 2017). "Rodent studies have suggested that resistin protein is a link between obesity, insulin resistance, and diabetes." (PMID 29075331, 2017). "Because of its link with obesity, inflammation, and insulin resistance, resistin has been tagged as a potential marker of MetS." (PMID 29075331, 2017). "In that study, the meal replacement group had a pronounced reduction in adipokines fetuin A and resistin compared to the lifestyle group, reinforcing the potential anti-obesity effect of soy in humans." (PMID 28835674, 2017). "The adipokines resistin and TNF-α regulate the lipid and glucose metabolisms and their elevated levels have been associated with the progression of obesity and diabetes." (PMID 27775654, 2016). "The aim of study was to evaluate the relationship between serum resistin andleptin levels with obesity and coronary artery disease (CAD)." (PMID 27627223, 2016). "In the present study, the negative association between adiponectin levels and gestational BMI (r = −0.28) suggests that the higher the degree of obesity, the higher the insulin resistance, with lower adiponectin and higher resistin levels expected." (PMID 27651836, 2016). "One of the five PC metabolites, PC aa C38:5, is associated with a number of inflammation markers and adipokines associated with increased obesity and insulin resistance, including C-reactive protein (CRP) and resistin." (PMID 27249024, 2016). "In this study we investigated the potential role of aqueous extracts of tomato and broccoli grown in Egypt in regulating blood glucose level in HFD-induced obesity in rats, as well as the possible role of resistin in maintenance of glucose homeostasis." (PMID 27430475, 2016). "This study reports for the first time that both broccoli and tomato extracts improved glucose homeostasis in HFD-induced obesity rats, possibly through the reduction of resistin in addition to their high nutritional value." (PMID 27430475, 2016). "The overexpression of resistin results in the accumulation of intracellular lipid and then leads to obesity-mediated insulin resistance and inflammation." (PMID 27642602, 2016). "Maternal and fetal glucose, lipid profile, adiponectin, leptin, and resistin levels were analyzed by obesity and maternal weight gain." (PMID 27190514, 2016). "The downstream target genes of PPARγ and C/EBPα, such as aP2 and adiponectin, are involved in maintaining the adipocyte phenotype, and resistin has been reported as a link between obesity and diabetes." (PMID 27143989, 2016). "Because of its inflammatory properties and role in adipose tissue, resistin is being investigated as a link between inflammation, obesity, and cancer." (PMID 27314854, 2016). "Human resistin is primarily expressed in macrophages, and its expression in human AT induces the production of inflammatory cytokines in obesity." (PMID 27101398, 2016). "Though resistin has been proposed to be a key between insulin resistin and obesity in animal models, the role of resistin in metabolic disorders in humans is not obvious." (PMID 27246401, 2016). "Although the plasma level of resistin, a major pathological factor in obesity, metabolic disorders, and diabetes, was unchanged in our model, the role of other adipokines and cytokines remain to be further studied." (PMID 26537347, 2015). "Actually, IL-6, MCP-1, resistin, and TNF-α are associated strongly with obesity-induced inflammation and obesity-related pathologies." (PMID 26248075, 2015).
Obesity (continued). "This clearly has implications for individuals with T2DM, as resistin levels have been measured in relation to obesity, T2DM and the metabolic syndrome, and are known to be variably increased in these conditions." (PMID 26295162, 2015). "The initial discovery of resistin and resistin-like molecules (RELMs) in rodents suggested a role for these adipocytokines in molecular linkage of obesity, Type 2 Diabetes mellitus and metabolic syndrome." (PMID 26097512, 2015). "Obesity is accompanied by increased release of free fatty acids (FFAs) and altered secretion of adipokines such as leptin, adiponectin, resistin and retinol-binding protein-4 (RBP-4) from adipocytes." (PMID 26110385, 2015). "Increased resistin concentration has been observed in mice with genetically and diet-induced obesity." (PMID 26681840, 2015). "This protein has recently been demonstrated to be a functional receptor for human resistin, coordinating resistin-mediated inflammation in obesity." (PMID 25691058, 2015). "Previous studies showed that resistin regulates insulin sensitivity and glucose metabolism, and is a mediator between diabetes and obesity, exhibiting a positive correlation with body mass index." (PMID 25980409, 2015). "This produced inconsistent or conflicting reports of serum resistin levels in relation to obesity and diabetes." (PMID 26097512, 2015). "In addition, bioactive molecules and hormones associated with obesity (such as leptin, angiotensinogen, aldosterone stimulating factor, dipeptidyl peptidase 4, and resistin) that could explain the metabolic effect of adipose tissue on glomerular hyperfiltration were not measured." (PMID 26495973, 2015). "Accordingly, elevated serum resistin level is detected in obesity and in a variety of malignancies such as colorectal cancer, breast cancer, non-small cell lung cancer and prostate cancer." (PMID 25980409, 2015). "In humans levels of RELMβ elevate during high-fat diets and obesity, increasing resistance to insulin in a manner similar to resistin." (PMID 26097512, 2015). "Correlation between leptin and resistin and the inflammatory markers was found to be highly dependent on obesity, in contrast to the one between adiponectin and TNF-α." (PMID 24736687, 2014). "In animal models, resistin promotes insulin resistance, while the evidence for this effect in human is less clear, so that it was proposed as potential link between obesity and diabetes." (PMID 24741591, 2014). "This study aimed to analyse the impact of obesity in type 2 diabetes (T2D) on adipocytokines (adiponectin, leptin and resistin) and inflammatory markers (TNF-α, IL-6 and hsCRP) as cardiovascular risk factors." (PMID 24736687, 2014). "There is a genetic evidence to support relationships between human inflammation, in particular resistin and obesity or IR." (PMID 25551102, 2014). "Data suggests that resistin plays a role in obesity, insulin resistance, cardiovascular diseases, and periodontitis." (PMID 24692844, 2014). "Resistin, also known as Fizz3, is a 12-kDa cysteine-rich protein that plays a role in the development of insulin resistance and obesity in rodents." (PMID 24829560, 2014). "In contrast, leptin and resistin correlated with the inflammatory markers, and this correlation was obesity-dependent." (PMID 24736687, 2014). "Resistin is another adipokines that was found to be increased in a diet induced obesity mouse model, as well as genetically modified diabetic and obese mouse models." (PMID 24716628, 2014). "It has been suggested that the adipokine resistin links obesity and insulin resistance, although how resistin acts on muscle metabolism is controversial." (PMID 25217974, 2014). "In mice, neutralization of resistin by antibody improved glucose and insulin action in diet-induced obesity." (PMID 24692844, 2014).
Obesity (continued). "Three main adipokines, resistin, adiponectin and leptin are adipocyte-secreted molecules that act as core contributors to the development or regulation of obesity, insulin resistance and hepatic steatosis." (PMID 24879081, 2014). "Since the discovery of resistin, most studies have focused on the relationship of resistin to obesity and diabetes." (PMID 24929539, 2014). "Reports on the levels of circulating resistin found in individuals with obesity and T2DM is controversial, but it is clear that resistin is associated with reduced insulin sensitivity." (PMID 25386661, 2014). "Thereafter, widespread research on the relationship between resistin and obesity highlighted its role in OS-related cardiovascular disease." (PMID 25548896, 2014). "Several reports have shown increased TNF-α, IL-6, resistin and leptin expression in obesity, type 2 diabetes, cardiovascular disease and metabolic syndrome." (PMID 24481132, 2014). "The expression and secretion of leptin, resistin, and TNF-α have been associated with the progression of obesity, while the adiponectin has been shown to be inversely related with obesity and has anti-inflammatory and anti-atherosclerotic properties." (PMID 24932656, 2014). "Nampt and resistin are proinflammatory adipokines secreted from adipocytes, monocytes, and macrophages for which differential relationships in obesity and type 2 diabetes have been described." (PMID 24968098, 2014). "Obesity is characterized by increase in the adipose tissue, which is an important source for various pro-inflammatory cytokines such as resistin, TNF-α, IL, visfatin, and adiponectin." (PMID 24692844, 2014). "With human obesity elevated serum resistin levels were observed when compared with humans in lean condition." (PMID 23634778, 2013). "The discovery of resistin has led the way to intense research in the area of fat-derived mediators in obesity-induced insulin resistance and T2DM." (PMID 24072088, 2013). "Initial studies showed that circulating resistin levels were increased in diet-induced and genetic obesity mice and decreased by the anti-diabetic drug rosiglitazone." (PMID 23776497, 2013). "In rodents, initial studies reported increased resistin levels in various models of obesity and insulin resistance." (PMID 24455420, 2013). "This discovery suggests that deregulation of resistin induces insulin resistance in genetic models (ob/ob and db/db) and in a diet-induced model of diabetes and obesity." (PMID 23634778, 2013). "Along with furin and MT1-MMP, resistin, an adipokine typically increased in obesity as well as atherosclerosis, was coordinately upregulated in monocytes from obese patients." (PMID 23936445, 2013). "IL-6, MCP-1, resistin, and TNF-α are associated strongly with obesity-induced inflammation and obesity-related pathologies." (PMID 24049664, 2013). "The physiological, metabolic and pro-inflammatory role of different adipokines, such as, leptin, resistin, visfatin will be discussed individually and according to the role each plays in diabetes, obesity, and immunity." (PMID 23634778, 2013). "In the present study, we sought to investigate the expression profiles of resistin in db/db mice, a widely used classical model of obesity and diabetes, at different ages (from 5 to 12 weeks) and its association with metabolic parameters." (PMID 23776497, 2013). "Administration of anti-resistin antibody improved blood sugar and insulin action in mice with diet-induced obesity." (PMID 23776497, 2013). "Some of the adipokines hormones such as leptin, adiponectin, resistin, and ghrelin play a role in the regulation of glucose metabolism and are involved in the development of obesity, diabetes, inflammation, auto-immunity and metabolic syndromes." (PMID 23634778, 2013). "Recently, resistin has been proposed to play an important role in the pathogenesis of obesity-related insulin resistance." (PMID 23634778, 2013).
Obesity (continued). "Therefore, the role of resistin in obesity-associated insulin resistance remains unclear." (PMID 23776497, 2013). "The physiologic role of resistin in obesity and type 2 diabetes mellitus has been the subject of much controversy." (PMID 23691290, 2013). "Several genes were differentially expressed including resistin, an adipocytokine involved in insulin resistance, obesity, and breast cancer, which had over four times higher expression in AA patients." (PMID 24324792, 2013). "Previous studies have postulated the controversial role of resistin in obesity and insulin resistance." (PMID 23634778, 2013). "The elevated values at baseline in both groups confirmed previous observations that resistin links obesity and inflammation." (PMID 23744123, 2013). "Because MCP-1 is the major chemoattractant derived from obese WAT, and resistin is abundantly found in circulating MNCs in obesity, regulation of furin, serpinB8 and MT1-MMP by these adipokines was compared." (PMID 23936445, 2013). "Moroever, in inflammasome, deficient animals which are protected against the development of high-fat diet (HFD), induced obesity and insulin resistance, the production of protein resistin is significantly reduced." (PMID 23484124, 2013). "The current review summarizes the recent knowledge regarding the malfunction of adipokines such as leptin, resistin, and visfatin in the initiation and progression of many metabolic diseases including obesity, diabetes and immunity." (PMID 23634778, 2013). "Further discovery have shown that various adipokines, such as adiponectin, visfatin, resistin are produced in adipose tissue and involved in the pathophysiology of obesity." (PMID 22474595, 2012). "Our results suggest that T3 modulate serum and gene expression levels of leptin, resistin, and adiponectin in experimental model of obesity, providing new insights regarding the relationship between T3 and adipokines in obesity." (PMID 22645452, 2012). "There has been a link between circulating resistin and low-grade inflammation that accompany obesity." (PMID 22567283, 2012). "Resistin expression in vivo is specific to white adipose tissue and circulates in mouse serum, and its level is increased in both genetic and diet-induced obesity." (PMID 22848362, 2012). "In opposition to most other adipocyte-derived cytokines (leptin, resistin, adipsin, etc.), adiponectin levels are decreased in obesity (probably through TNFα and IL-6 downregulation)." (PMID 22584415, 2012). "Although most reports concerning resistin focused on its function in the metabolic syndrome, obesity, and IR, there is some evidence on its role in RA and other inflammatory diseases." (PMID 22584415, 2012). "The signaling molecule resistin (for resistance to insulin) has enhanced circulating levels during obesity and diabetes." (PMID 22545721, 2012). "Adipokines such as adiponectin, visfatin, and resistin are involved in the physiology of obesity and those genes show circadian rhythmicity." (PMID 22474595, 2012). "Several studies involving leptin, adiponectin and resistin, have individually shown pleiotropic effects to obesity-related phenotypes with significant heritability estimates." (PMID 21483749, 2011). "Circulating resistin levels are decreased by the anti-diabetic drug rosiglitazone and are increased in diet-induced and genetic forms of obesity." (PMID 21686173, 2011). "Administration of the anti-resistin antibody improves blood sugar and insulin action in mice with diet-induced obesity." (PMID 21686173, 2011). "Resistin expression is stimulated by TNFα and IL-6, both of which are increased in obesity, which offers an explanation for an increased level of resistin in obesity." (PMID 21410966, 2011). "Serum adipokine levels are known to be dysregulated in obesity, with downregulation of adiponectin and upregulation of leptin and resistin." (PMID 21813022, 2011).
Obesity (continued). "Adiponectin levels inversely correlate with BMI and are lower in individuals with diabetes whereas resistin directly correlates with obesity and insulin resistance." (PMID 21676224, 2011). "In genetic and diet induced mouse models of obesity resistin levels were elevated and therefore was concluded to be a link between obesity and insulin resistance." (PMID 20360975, 2010). "In rodents, resistin is derived almost exclusively from adipose tissue, and serum resistin is elevated in animal models of obesity and insulin resistance." (PMID 19922611, 2009). "The state of obesity is accompanied by changes in the expression and secretion of adipokines including adiponectin and resistin, and by an increased release of FFA from hypertrophied adipocytes." (PMID 19956652, 2009). "Our Bioinormatics analysis once again heightens the possible role of Resistin gene that connects obesity and diabetes mellitus." (PMID 23675069, 2008). "The discovery of an adipose-specific secreted protein called ‘resistin’ which circulates in the mouse, with increased levels in obesity, and has effects on glucose homeostasis that oppose those of insulin." (PMID 21876654, 2008). "Resistin (RETN), another member of this group, is an adipocyte-secreted protein involved in type II diabetes and obesity and its identification provides a further link between energy metabolism and inflammatory responses in mammary tissue." (PMID 18513449, 2008). "A variety of factors have been proposed to explain the obesity-related endothelial dysfunction including alteration in the adipocyte-derived hormones resistin, adiponectin and leptin, high plasma triglycerides concentration and increase of oxidative stress." (PMID 18510739, 2008). "Accordingly, an increasing number of reports have raised doubts regarding the possibility of an important relationship between human resistin and various metabolic disturbances characteristic of obesity and type 2 diabetes." (PMID 17479165, 2007). "Much of the work on resistin has been done in mice, and as a result of this research the hormone was thought to explain the link between obesity and development of diabetes." (PMID 17479165, 2007). "Resistin is an example of an important adipocyte secreted protein, and elevated resistin levels in adipose tissues and serum are observed in both genetic and diet-induced obesity and insulin resistance in animal models." (PMID 16854242, 2006). "Recently, mouse resistin was described as a novel obesity-mediated adipocytokine that impairs glucose homeostasis by affecting both insulin-stimulated glucose uptake in adipose tissue and hepatic glucose production during fasting." (PMID 17183659, 2006). "More research is necessary to confirm these findings and to find out how important resistin is as a link between obesity and diabetes, and how resistin promotes diabetes." (PMID 15578112, 2004). "Clearly the relationship between obesity, inflammation, and resistin expression is complex, and needs to be systematically studied in larger and varied patient populations." (PMID 15578112, 2004). "In this context it is intriguing that resistin levels are increased in obesity and that insulin-sensitizing agents such as aspirin and rosiglitazone, with disparate primary molecular targets, antagonize resistin induction." (PMID 15578112, 2004). "The increased level of resistin in humans with obesity is likely an indirect result of elevated levels of inflammatory cytokines characteristic of states of increased adiposity." (PMID 15578112, 2004). "Our data suggest that, whereas hyperresistinemia in obese rodents derives directly from adipocytes, human resistin is indirectly regulated by the inflammatory internal milieu of obesity." (PMID 15578112, 2004). "Future work will be needed to better understand the relationship between circulating resistin levels and the insulin resistance characteristic of inflammatory states, including obesity." (PMID 15578112, 2004).